LPCAT4 (lysophosphatidylcholine acyltransferase 4)
Description:
Displays acyl-CoA-dependent lysophospholipid acyltransferase activity with a subset of lysophospholipids as substrates; converts lysophosphatidylethanolamine to phosphatidylethanolamine, lysophosphatidylcholine to phosphatidycholine, 1-alkenyl-lysophatidylethanolamine to 1-alkenyl-phosphatidylethanolamine, lysophosphatidylglycerol and alkyl-lysophosphatidylcholine to phosphatidylglycerol and alkyl-phosphatidylcholine, respectively. In contrast, has no lysophosphatidylinositol, glycerol-3-phosphate, diacylglycerol or lysophosphatidic acid acyltransferase activity. Prefers long chain acyl-CoAs (C16, C18) as acyl donors.
Synonyms: AGPAT7; AYTL3; LPEAT2; FLJ10257; LPAAT-eta; LPLAT10
Tractability: Antibody: UniProt predicts a signal peptide or a membrane-spanning region. PROTAC: ubiquitination databases record sites on it; its protein half-life has been measured.
Gene: Protein-coding gene on chromosome 15 (34,358,633 to 34,367,539, reverse strand). Ensembl gene ENSG00000176454.
Subcellular location: Endoplasmic reticulum membrane
Pathways (Reactome):
Metabolism: Acyl chain remodelling of PC; Acyl chain remodelling of PE; Acyl chain remodelling of PG; Acyl chain remodelling of PS; Synthesis of PA
Gene Ontology:
Molecular function: 1-acylglycerophosphocholine O-acyltransferase activity; 1-acylglycerophosphoethanolamine O-acyltransferase activity; 1-acylglycerophosphoserine O-acyltransferase activity; 1-alkenylglycerophosphoethanolamine O-acyltransferase activity; 1-alkylglycerophosphocholine O-acetyltransferase activity; 2-acylglycerophosphocholine O-acyltransferase activity; lysophospholipid acyltransferase activity; 1-acylglycerol-3-phosphate O-acyltransferase activity; 2-acylglycerol-3-phosphate O-acyltransferase activity; lysophosphatidic acid acyltransferase activity; 1-alkylglycerophosphocholine O-acyltransferase activity; acyltransferase activity
Biological process: phosphatidylcholine acyl-chain remodeling; phosphatidylethanolamine acyl-chain remodeling; phosphatidylserine acyl-chain remodeling; phospholipid metabolic process; phosphatidic acid biosynthetic process; phosphatidylglycerol acyl-chain remodeling
Cellular component: endoplasmic reticulum; endoplasmic reticulum membrane; membrane
Genetic constraint (gnomAD): Loss-of-function variants: 30 observed, 66.07 expected, observed/expected ratio (o/e) 0.45, 90% interval 0.34 to 0.62. The upper end of that interval is the gene's LOEUF score, 0.62, which puts it in group 2 of 6, group 1 being the genes least tolerant of losing a copy. Missense variants: 549 observed, 657.27 expected, observed/expected ratio (o/e) 0.84, 90% interval 0.78 to 0.9. Synonymous variants: 252 observed, 261.31 expected, observed/expected ratio (o/e) 0.96, 90% interval 0.87 to 1.07.
Homologues: Orthologues: chimpanzee LPCAT4 (99% identical), macaque LPCAT4 (98% identical), mouse Lpcat4 (93% identical), pig LPCAT4 (93% identical), rat Lpcat4 (93% identical), guinea pig LPCAT4 (92% identical), dog LPCAT4 (89% identical), rabbit LPCAT4 (76% identical), tropical clawed frog lpcat4 (51% identical), zebrafish lpcat4 (39% identical), Drosophila melanogaster LPCAT (30% identical). Paralogues in human: LPCAT2 (41% identical), LPCAT1 (35% identical), GPAT4 (15% identical), GPAT3 (15% identical).
Diseases named in the same sentence as LPCAT4 in open-access papers:
LPCAT4 is named in the same sentence as 13 diseases in open-access papers, as found by Europe PMC text mining. Sharing a sentence is not in itself a finding about the gene and the disease. The quoted sentences say what the papers report.
colorectal cancer (2 papers, 2023). A primary or metastatic malignant neoplasm that affects the colon or rectum. "The ratio of PC to Lyso-PC has been implicated as a biomarker for colorectal cancer, indicating LPCAT4 as a key factor for improving standard of care for colorectal cancer." (PMID 37250116, 2023). "Abnormal expression of LPCAT4 was involved in the progression of colorectal cancer and prostate cancer." (PMID 37294538, 2023). "LPCAT4’s expression is upregulated in colorectal cancer cells." (PMID 37250116, 2023). "LPCAT2 and LPCAT4 contributes to initiation and chemoresistance in colorectal cancer." (PMID 37294538, 2023).
hepatocellular carcinoma (2 papers, 2023 to 2024). A malignant tumor that arises from hepatocytes. "LPCAT4 enhanced cell growth and cholesterol biosynthesis by up-regulating ACSL3 in hepatocellular carcinoma (HCC)." (PMID 37294538, 2023). "LPCAT4 activates the WNT-β-catenin pathway in cancer cells, leading to increased cholesterol synthesis, which suggests that LPCAT4 may be a therapeutic target for the treatment of hepatocellular carcinoma." (PMID 38893234, 2024).
Obesity (2 papers, 2018 to 2023). Accumulation of substantial excess body fat. "This placental response to obesity may be a compensatory mechanism in response to deficient phospholipid remodeling pathway as indicated by the decreased expression of LPCAT4 in female placentas." (PMID 37770949, 2023). "On the other hand, untargeted lipidomics analysis showed that phospholipids of specific molecular species were significantly reduced in the colonic epithelium from young obese mice, in keeping with obesity-associated dysregulation of phospholipid metabolism genes, such as Lpcat1 and Lpcat4." (PMID 29346762, 2018). "PLA2G4C abundance was lower in male placentas and LPCAT4 abundance was lower solely in females in obesity." (PMID 37770949, 2023).
articular cartilage disorder (1 paper, 2017). A disease involving the articular cartilage of joint. "LPCAT4 may have potential as a therapeutic target for articular cartilage disorders." (PMID 29196633, 2017).
breast carcinoma (1 paper, 2023). "Next, we performed correlation analysis of the protein levels of PNPLA8 and LPCAT4 with the detected lipid abundances in the tested panel of breast cancer cell lines, which was based on our Western Blot and lipidomic analysis results." (PMID 38017485, 2023). "LPCAT4 protein levels were downregulated in most of the breast cancer cell lines, and lower mRNA levels of LPCAT4 were associated with longer relapse-free survival in breast cancer patients." (PMID 38017485, 2023). "In addition to PNPLA8, we also detected LPCAT4 mRNA and protein levels to be downregulated in breast cancer cell lines." (PMID 38017485, 2023). "Overall, the mRNA and protein expressions of PNPLA8 and LPCAT4 were consistently dysregulated in the tested panel of breast cancer cell lines, and both gene expression levels were correlated with relapse-free survival in breast cancer patients." (PMID 38017485, 2023).
colon cancer (1 paper, 2017). "The LPCAT1, which converts LPC into PCs, is overexpressed in several cancers and is associated with colon cancer growth showed that LPCAT4 was overexpressed in CRC and contributes to PC (16:0/16:1) accumulation via the enhanced re-acylation of LPC." (PMID 29359123, 2017).
glioblastoma (1 paper, 2023). The most malignant astrocytic tumor (WHO grade IV). "However, the expression of AGPAT7/LPEAT2/LPCAT4 is lower in glioblastoma tumors than in healthy brain tissue." (PMID 37046844, 2023).
cancer (3 papers, 2017 to 2024). A tumor composed of atypical neoplastic, often pleomorphic cells that invade other tissues. "LPCAT4 is also implicated in cancer, with its expression decreased in colorectal cancer, suggesting an anticancer nature." (PMID 38893234, 2024). "With the use of the Cancer Cell Line Encyclopedia (CCLE) database, we uncovered that LPCAT4 was expressed in a majority of LIHC cell lines." (PMID 37294538, 2023).
LPCAT4 also shares sentences with these, for which no sentence is quoted: cervical cancer (1 paper); inflammatory bowel disease (1); lung carcinoma (1); lymphoma (1); prostate carcinoma (1).